SMAD4 (SMAD family member 4)
Diseases named in the same sentence as SMAD4 in open-access papers (continued):
Sharing a sentence is not in itself a finding about the gene and the disease.
tumor (continued). "To elucidate the mechanism underlying the inhibition of tumor growth mediated by PostB, we examined the protein expression of autophagy pathway markers, such as PI3K, AKT, mTOR, TGF-β, and SMAD4, in the tumor tissues of CT26.WT-bearing mice by Western blotting." (PMID 39459634, 2024). "miR301a-3p is an oncogene targeting many tumor suppressor genes, such as Smad4 in LSCC." (PMID 38238286, 2024). "SMAD4, a transforming growth factor (TGF)-β/BMP signaling effector and a tumor suppressor, is frequently mutated in PDAC and actively participates in the interaction between cancer and stromal myeloid cells and mediates the response of cancer cells to stromal chemokine." (PMID 38378604, 2024). "Two-way ANOVA revealed that the induction of early-stage CRC significantly affected the downregulation of the Apc gene, which is a critical regulator in the WNT signaling pathway and a known tumor suppressor gene, as well as the Smad4 gene, also a suppressor gene (ANOVA, p < 0.05)." (PMID 38674816, 2024). "Smad4 acts as a tumor suppressor in CRC; however, the role of Smad4-mediated signaling in the immune microenvironment of CRC remains controversial Smad4 deletion in human CRC cells resulted in the recruitment of more neutrophils through the CXCL1/8-CXCR2 axis to promote CRC progression." (PMID 39664586, 2024). "As a tumor suppressor, Smad4 plays an important role in colorectal carcinogenesis and invasiveness." (PMID 39664586, 2024). "Notably, we found that neutralizing CXCL10 abolished the tumor-suppressive effects of Smad4 knockdown, indicating that CXCL10 inhibition by Smad4 was crucial for its oncogenic activity." (PMID 39346534, 2024). "In contrast, changes in SMAD4 are directly related to the molecular and cellular mechanisms of the tumor, providing more in-depth information on disease pathology and having potential value in understanding tumor aggressiveness and predicting treatment responses." (PMID 39164192, 2024). "In addition, we assessed the requirement for SMAD4 in tumor cell-specific BMP signalling by expression of a constitutively active BMP receptor." (PMID 38689334, 2024). "Additionally, in the DSS/AOM CRC tumor model, flow cytometry was utilized to detect the protein expression of Smad4 in NKp46+NK cells." (PMID 39439794, 2024). "BMP4 can also signal through a non-canonical pathway, particularly in cells with loss of SMAD4, a common tumour suppressor gene, resulting in the activation of PI3K/AKT, NF-κB and MAPK pathways capable of promoting tumour progression." (PMID 39273106, 2024). "In CRC patients undergoing chemotherapy or radiotherapy, changes in SMAD4 levels may indicate the degree of tumor response to treatment." (PMID 39164192, 2024). "Also in tumor TME, the role of SMAD4 in tumors and tumor immunity is complicated, it can serve as both a tumor promoting factor and a tumor suppressor, playing a double-edged sword role." (PMID 39439794, 2024). "The role of SMAD4 in the CRC microenvironment extends beyond its function as a tumor suppressor." (PMID 39164192, 2024). "Although SMAD4 plays a crucial role in tumor prognosis and antitumor immunoregulation, its importance in the prognosis and immune response in HPC remains unclear." (PMID 37035326, 2023).
tumor (continued). "Similarly, miR-450b-5p, suppressed in RMS by TGF-β1 through a pathway mediated by Smad3 and Smad4, exerted anti-tumour effects in tumour implants and cells by arresting RMS growth and upregulating MyoD expression." (PMID 36765536, 2023). "Vehicle-treated organoids developed projections and were able to migrate through the matrix as previously seen, while pINDUCER-SMAD4 tumor organoids expressing SMAD4 showed that many organoids retained spherical morphology and did not appear to develop projections." (PMID 38136364, 2023). "Smad4 also induced the angiogenesis in ovarian cancer and increased the tumor development." (PMID 37580768, 2023). "We then wanted to know whether SMAD4 restoration would result in a significant tumor volume reduction in vivo." (PMID 37377893, 2023). "Interestingly, SMAD4 re-expression within the tumor organoids results in a significant reduction in invasive capability, indicative of a direct role of SMAD4 in suppression of serrated cancer invasion." (PMID 38136364, 2023). "Finally, loss of SMAD4 in metastatic tumor organoids has increased secretion of DKK3, which inhibits NK cell activity, providing evidence of SMAD4 loss influencing tumor immune response." (PMID 38136364, 2023). "As seen, a modulator possessing the activities on uPAR and MYC, an oncogene, could be prone to affecting cell proliferation and survival, whereas one possessing the activities on uPAR and SMAD4, a tumor suppressor gene, could affect angiogenesis and migration." (PMID 37895906, 2023). "For the BRAF, PIK3CA, and SMAD4 genes, no eligible studies were found that investigated the role of genetic tumor mutations on tumor downstaging." (PMID 36900260, 2023). "SMAD4 is a tumor suppressor gene that plays a central role in TGF-β signaling pathway transduction." (PMID 36969909, 2023). "Furthermore, tumor epithelial expression of SMAD4 in cytoplasm (HR 0.58, 95% CI 0.43–0.80, p < 0.001) and RUNX3 in nucleus (HR 0.62, 95% CI 0.45–0.84, p = 0.002) were independent positive predictors of DSS." (PMID 36900240, 2023). "Somatic inactivation of Smad4 is a frequent event in multiple tumor types." (PMID 38003328, 2023). "Smad4 somatic silencing is frequently encountered in a variety of tumor types." (PMID 38129938, 2023). "Smad4 was first identified as a tumor suppressor in pancreatic cancer and later as a TGF-mediator." (PMID 38003328, 2023). "Given LOF mutations in SMAD4 cause JPS, it is hypothesised that gain-of-function mutations observed in MS may contribute to neoplasia." (PMID 38066625, 2023). "Measuring the levels of TAp73 and/or SMAD4 could help to predict whether TGF-β preferentially uses an oncogenic or a tumor suppressive pathway in a given patient and at a specific time." (PMID 37568607, 2023). "This suggests that the tumor-suppressive role of SMAD4 may be more complex than just simple antagonism of proliferation." (PMID 38136364, 2023). "Thus, it would be exciting to further delve into the conditions for SMAD4-dependent gene regulation in different tumor microenvironments, and the continued use of organoid modeling provides a powerful foundational tool in these future studies." (PMID 38136364, 2023). "Although loss of function of SMAD4 does not directly initiate tumorigenesis, it can promote tumor progression initiated by other genes, such as APC." (PMID 36831263, 2023).
tumor (continued). "Furthermore, extensive correlations between IRS-1 and IRS-2, RUNX3 and SMAD4 in tumor and stroma, were observed (0.15 < r < 0.60)." (PMID 36900240, 2023). "We hypothesized that circLDLRAD3 may exert tumour suppressor effects by regulating the expression of miR‐558 as well as its target gene Smad4." (PMID 37563869, 2023). "In livers of nude mice, SMAD4-deficient human CRC cells (AA/C1, HT29, Colo205, LoVo, DLD-1, and HCT116) displayed CCL15 upregulation and increase in CCR1(+) cells recruitment that promoted tumor invasion." (PMID 37185750, 2023). "Moreover, Smad4 deletion in mouse tissues, together with other genetic changes that trigger tumor growth, resulted in cancer lesions in colon, pancreas, stomach, and liver." (PMID 38129938, 2023). "In PDAC, TGFβ encourages tumor growth by regulating EMT through SMAD4." (PMID 38028629, 2023). "In contrast, if the tumor displays SMAD4 loss of expression, we did not observe a statistically significant difference in terms of survival between Gemcitabine- and FOLFIRINOX-based NAT." (PMID 37568581, 2023). "The Smad4 protein is involved both as a transcription factor and a tumor suppressor." (PMID 36807774, 2023). "Subsequent genetic experiments showed that ablating Prdm16 along with Smad4 resulted in a shift from a well-differentiated and confined neoplasm to a highly aggressive and metastatic disease, which was associated with a striking deviation in the trajectory of the premalignant lesions." (PMID 36828547, 2023). "RAB10 is important for the proliferation of SMAD4-altered tumor cells." (PMID 37377893, 2023). "Notably, E-cadherin and Smad4, the essential mediators of this elimination system, are also tumor-suppressor genes, and loss-of-function of either E-cadherin or Smad4 prevented Wnt/β-catenin-hyperactivated cells from apoptotic elimination in zebrafish." (PMID 37164759, 2023). "This study suggests that the role of SMAD4 as a tumor suppressor is more complex than currently appreciated and may have implications in the understanding of cancer invasion." (PMID 38136364, 2023). "For patients with resectable PDAC, a combination of KLF10 and SMAD4 expression in tumor tissues may help select those who may benefit the most from additional radiotherapy." (PMID 37958386, 2023). "In univariate analyses, high expression levels of IRS1 in stromal cytoplasm, RUNX3 in tumor (nucleus and cytoplasm) and stroma (nucleus and cytoplasm), and SMAD4 in tumor (nucleus and cytoplasm) and stromal cytoplasm were related to increased disease-specific survival (DSS)." (PMID 36900240, 2023). "More potential LM progression-related markers were detected in CSF samples than in tumor samples, including PREX2 mutation (P = 0.014), IGF1R mutation (P = 0.034), AR mutation (P = 0.038), SMARCB1 deletion (P < 0.001), SMAD4 deletion (P = 0.0034), and TGF-beta pathway aberration (P = 0.0038)." (PMID 37131253, 2023). "The deletion of SMAD4, often observed in advanced tumour stages and lymph node involvement, is typically accompanied by decreased peritumoral lymphocyte aggregation and a lower presence of tumor‐infiltrating lymphocytes (TILs)." (PMID 37488750, 2023).
tumor (continued). "This study reveals that SMAD4 is a critical tumor suppressor for BRAF-driven serrated tumors." (PMID 38136364, 2023). "This invasive behavior can be suppressed when SMAD4 is re-expressed in the tumor organoids." (PMID 38136364, 2023). "In addition to its role in TGF signalling, Smad4 increases immune cell infiltration, which makes the tumour more sensitive to therapy." (PMID 38067256, 2023). "As a tumor suppressor, Smad4 is inactivated in various cancers." (PMID 37654657, 2023). "Considering the effect of miR‐558 on Smad4, we next explored whether circLDLRAD3 execute its tumour suppressor effect through Smad4." (PMID 37563869, 2023). "Their results indicate that tumor SMAD4 signaling interacts with the tumor micro-environment." (PMID 36900240, 2023). "Thus, ASLNC07322 overexpression abrogates the tumor-suppressive effect of SMAD4, leading to the uncontrolled expression of VEGF-C, which in turn promotes tumor lymphangiogenesis and lymphatic metastasis." (PMID 37407839, 2023). "Nonetheless, both driver gene variants (KRAS p.G12V, SMAD4 p.A39T) identified by bulk WES of this same sample were identified with high-quality read data and indicated 113 likely tumor cells (23.6% of all) captured for this sample based on the presence of the clonal KRAS variant." (PMID 36765116, 2023). "Smad4 was regarded as an important tumour suppressor in various types of cancers." (PMID 37563869, 2023). "Herein we proved a robust evidence in support of in vivo interaction between GATA2 and SMAD4 and thus sought to unravel the mechanistic roles of TGFβ1/SMAD4 in the GATA2-dependent context in PCa tumor progression to advanced stages and to understand how GATA2 and SMAD4 mediate inherited PCa risk." (PMID 37550764, 2023). "The SMAD4-p.His530ThrfsTer47 and KRAS-p.Gly12Val mutation might promote the occurrence and distant metastasis of the tumor." (PMID 35299731, 2022). "SMAD4 plays the critical intracellular signal transduction mediator in the TGF-β pathway; the protein deletion is currently associated with lymph-node metastases, increased angiogenesis in vitro, and more aggressive tumor behavior in patients." (PMID 35887766, 2022). "SMAD4 is a tumor-suppressor gene, acting as a downstream regulator of the TGF-β pathway." (PMID 35049691, 2022). "To further investigate whether inhibition of BMP4 and BMP2/4 in SMAD4(-) ISO76A cells could attenuate tumor growth and potentiate the effect of cisplatin in the PDX model, we compared the effects of C8C8 and C4C4 with and without cisplatin treatment in vivo." (PMID 35902550, 2022). "Correspondingly, analyses of human tumor transcriptomes showed that SMAD4 mutations were neither underrepresented, nor did they abrogate elevated expression of EMT-TFs in tumor samples exhibiting features of EMT." (PMID 34857888, 2022).
tumor (continued). "The SMAD4 pathway has been identified as a potential target for tumor treatment." (PMID 35723337, 2022). "We evaluated SMAD4 staining in the nuclei of tumor cells as functional SMAD4." (PMID 36088360, 2022). "SMAD4, a tumor suppressor, is a key mediator of the TGF-β signaling pathway." (PMID 35892903, 2022). "The analysis of tumor mutations with prevalence in less than 10% of patients with SMAD4 mutation was not included in our analysis as our sample size was not large enough to assess the impact of low-frequency alterations." (PMID 35892903, 2022). "The expression profile of SMAD4–201 in human tumor and non-tumor tissue samples may indicate the translational potential of this molecule in CRC, but further research is needed to clarify its usability as a potential biomarker for early diagnosis." (PMID 35034624, 2022). "The function of SMAD4 as a tumor suppressor and inhibits the proliferation of epithelial cells." (PMID 35075176, 2022). "SMAD4 was one of the 24 significantly mutated genes in the non-hypermutated tumours of the TCGA study." (PMID 35379892, 2022). "Additionally, we found that activation of TGFβ/SMAD4 signaling modestly reduced tumor cell expression of PD-L1 in vitro; however, SMAD4 and PD-L1 positively correlated in PDAC patient samples." (PMID 35155243, 2022). "In conclusion, our investigations based on human tumor transcriptomes revealed that SMAD4 mutations do not preclude elevated expression of EMT-TFs and the occurrence of gene expression patterns indicative of EMT in colorectal and pancreatic tumors." (PMID 34857888, 2022). "A signal transduction factor involved in tumor suppression and inhibition of epithelial cell proliferation, SMAD4 is activated in human umbilical vein endothelial cells following exposure to hypoxia and interacts with hypoxia-inducible factor-1 (HIF-1) to modulate hypoxia-driven gene expression." (PMID 35462239, 2022). "The role of KRAS/SMAD4 in the tumor microenvironment has additional value for exploration." (PMID 35887766, 2022). "However, a variety of other mutations exist, especially in tumor suppressor genes, such as CDKN2A, SMAD4, ARID1 or BRCA2." (PMID 36078040, 2022). "Possible explanations for this may be that SMAD4-mutant tumors escape the tumor-suppressive function of TGF-β or undergo SMAD4-independent EMT." (PMID 36430910, 2022). "Notably, SMAD4 suppresses tumor metastasis and promotes antitumor immunity through up-regulated IFN-γ and granzyme B (GZMB) by non-SMAD in NK cells at early stages." (PMID 35461253, 2022). "Here, a surprising function of Smad4 in suppressing mouse PDAC tumor immunogenicity is identified." (PMID 35064757, 2022). "SMAD4 expression was found in the cytoplasm and/or nucleus of tumor cells." (PMID 36088360, 2022). "It modulated the inhibitory effect of miR-100-5p on tumor suppressor gene SMAD4." (PMID 35525925, 2022). "Given that Smad4 deletion in tumor cells promoted the sensitivity to host immune response, we speculated that Smad4 deletion might enhance the tumor cells’ immunogenicity, which promoted immune recognition of tumor cells." (PMID 35064757, 2022).